ZEB1 (zinc finger E-box binding homeobox 1)
Diseases named in the same sentence as ZEB1 in open-access papers (continued):
Sharing a sentence is not in itself a finding about the gene and the disease.
breast carcinoma (continued). "Instead, MiR-205 may selectively regulate its oncogene target, such as Zeb1, which is normally highly expressed in cancers and thus lead to promoted EMT in malignancies, such as breast cancers." (PMID 27929537, 2016). "Second, both ZEB1 and VEGFA may induce the production of matrix metalloproteinases (MMPs), such as MMP-2 and MMP-9, in breast cancer cells." (PMID 26882471, 2016). "In this report, we have provided further evidence of a novel regulatory mechanism demonstrating that ZEB1 mediates the stimulation of VEGF synthesis and which may contribute to tumor growth and angiogenesis in breast cancer." (PMID 26882471, 2016). "Importantly, ZEB1 expression is positively correlated with VEGFA expression and blood vessel density in human breast cancer specimens." (PMID 26882471, 2016). "Our results indicate that there may be two mechanisms, both involving ER α and one requiring ZEB1, through which FXYD3 may be increased by estrogen and tamoxifen in breast cancer cells." (PMID 26090296, 2015). "Here, we demonstrate that specific silencing of LPA1 and ZEB1 inhibited the LPA-induced migration and invasion of basal breast cancer cell lines, supporting that ZEB1 is a downstream activated transcription factor of the LPA/LPA1 axis stimulating cell motility." (PMID 26098771, 2015). "Recently, the EMT-inducer ZEB1 was not only described as initiator of metastasis, but also to induce osteoclast formation and to inhibit osteoblast differentiation by regulating MMP1 expression in an in vitro system of breast cancer bone metastasis." (PMID 25973542, 2015). "To ensure that the absence of ZEB1 staining was not due to quality of antibody used or experimental conditions, we thus stained for ZEB1 expression in breast cancer tissues that have been previously reported to express the protein." (PMID 26214683, 2015). "In breast cancer, high expression of the EMT-inducer ZEB1 is strongly correlated with the estrogen receptor (ER) negative claudin-low subtype, which shows an intrinsic EMT phenotype, whereas its expression is very low in ER positive breast cancer cases." (PMID 25973542, 2015). "Therefore, nested feedback circuits of lnc-ATB/miR-200c/ZEB1 and lnc-ATB/miR-200c/ZNF217/TGF-β/ZEB1 contribute to EMT correlated with trastuzumab resistance and metastasis of breast cancer." (PMID 25871474, 2015). "Notably, different from the case in ESCC, these studies showed that miR-200 impact both the classic ZEB1/2-EMT pathway and the cytoskeleton reorganization process in breast cancer cells." (PMID 26334393, 2015). "Vimentin, Zeb1 and Sip1 are high in TNBC compared to non-TNBC cells and it was also shown that over expression of vimentin is associated with poor prognosis of breast cancer." (PMID 25268751, 2014). "There was also a considerable increase in the expression of others genes described as stem cell markers and expressed in CD44high fractions of normal and breast cancer tissues, including FOXC1(∼11-fold), IGFBP7 (∼8.5-fold), PROCR (∼8.2-fold), LEF1 (∼6.7-fold) and ZEB1 (∼6.6-fold)." (PMID 24498388, 2014). "Additionally, recent studies showed that GRHL2 and CDH1 in human breast cancer cells were highly correlated and suppressed EMT by repressing expression of the ZEB1 gene." (PMID 23887935, 2013). "Since miR-205 directly targets ZEB1 and ZEB2 in Madin Darby canine kidney cells, reduced expression of miR-205 could maintain breast cancer cells in the mesenchymal state through ZEB1/ZEB2 inhibition of E-cadherin (CDH1)." (PMID 24098490, 2013). "Furthermore, we have established a functional and reciprocal relation between ZEB1 and MYB that is prevalent in breast cancer systems." (PMID 24283570, 2013). "Indeed, we observed an inverse relation between MYB and ZEB1 expression in two in vitro EMT cell models, in matched human breast tumors and lymph node metastases, and in human breast cancer cell lines." (PMID 24283570, 2013).
breast carcinoma (continued). "The family of microRNAs 200 (miR-200a, miR-200b, miR-200c, miR-141 and miR-429) and the miR-205A regulate the expression of the transcriptional repressors of E-cadherin ZEB-1 and ZEB-2 and, consequently, the levels of E-cadherin in breast cancer cells and tissues." (PMID 23158001, 2012). "In our large set of breast carcinomas, no tumors were found with a positive nuclear expression of zeb1 in epithelial tumor cells." (PMID 21324165, 2011). "Additionally, in the MDA-MB-435 breast cancer cell line the presence of wild-type or mutant E-cadherin proteins leads to the differential regulation of a variety of EMT inducers (Snail, Twist, ZEB1, TCF3)." (PMID 19257890, 2009). "Additionally, TP73-AS1 promotes breast cancer cell proliferation and enhances mitogen activity by competitively binding to miR-200a at the 3′-UTR region of zinc finger E-box-binding homeobox 1 (ZEB1), thereby upregulating ZEB1 expression." (PMID 40332793, 2025). "In breast cancer cells, the involvement of NF-κB extends to mediating the expression of key EMT transcription factors, including Slug, Sip1, and Twist1,alongside NF-κB-dependent regulation of ZEB-1/ZFHX1A and ZEB-2/ZFHX1B, also known as Smad-interacting protein." (PMID 39493763, 2024). "The aim of this study was to investigate the inhibitory effect of miR-561-3p on ZEB1, HIF1A, and MYC expression as oncogenes that have the most impact on PD-L1 overexpression and cellular processes such as proliferation, apoptosis, and cell cycle in breast cancer (BC) cell lines." (PMID 38462658, 2024). "Studies have shown that ectopic Zeb1 directly increases the rate of glycolysis to determine the transcriptional expression of enzymes HK2, PFKP, and PKM2, thus promoting the Warburg effect and the proliferation, migration, and chemotherapy resistance of breast cancer in vivo and in vitro." (PMID 39596288, 2024). "This confirmed the absence of GRHL2 binding in the promoter of ZEB1 in luminal breast cancer cells." (PMID 36691073, 2023). "Thus, we determined the expression level of well-known EMT markers, including E-cadherin, Snail, Vimentin, and Zeb1, through RT-qPCR and immunofluorescence assays to assess whether PNKY can induce EMT in breast cancer cells." (PMID 37104007, 2023). "Another study indicated that in natural tamoxifen-resistant breast cancer cells (MDA-MB-231), the downregulation of linc-ROR could inhibit EMT and enhance sensibility to tamoxifen by increasing miR-205 expression and suppressing ZEB1 and ZEB2." (PMID 36827545, 2023). "Here, we show that ectopic Zeb1 directly increases the transcriptional expression of HK2, PFKP, and PKM2, which are glycolytic rate-determining enzymes, thus promoting the Warburg effect and breast cancer proliferation, migration, and chemoresistance in vitro and in vivo." (PMID 35246504, 2022). "ZEB1 could promote the E-cadherin expression and suppress the EMT of breast cancer cells." (PMID 35186455, 2022). "Interestingly, SIX1 promotes EMT of mammary carcinoma cells by increasing TGFβ signaling and regulates the transdifferentiation of colorectal cancer cells by post-transcriptional activation of the EMT-TF ZEB1." (PMID 35626752, 2022). "However, downregulation of ZEB1/2 through overexpression of miR-200, a known microRNA that directly targets ZEB1/2, in a mouse breast cancer model does not affect lung metastasis, but contributes to recurrent lung metastasis after chemotherapy." (PMID 36140527, 2022). "Moreover, TACC3 knockdown suppressed the expression of E-cadherin, but increased the expression of N-cadherin, Snail, ZEB1, and TWIST, which indicate that TACC3 may impact the migration of breast cancer cells in vitro." (PMID 34149795, 2021). "Interestingly, a significant negative correlation between CHFR and ZEB1 was observed in these breast cancer cells, in which most of the tumors with high ZEB1 expression exhibited low CHFR expression." (PMID 34462429, 2021).
breast carcinoma (continued). "Nonetheless, the benefits of modulating the Zeb1 transcriptional/epigenetic network in cancer immunotherapy have been clearly illustrated in the blockade of CD47, a direct transcriptional target of Zeb1, that enhances phagocytosis of breast cancer cells undergoing EMT." (PMID 33108352, 2021). "Further characterization of upcoming ZEB1-expressing tumor cells is needed to confirm this hypothesis, but one may suggest that ZEB1 and POLQ have opposite and complementary roles in the control of both the stability and integrity of breast cancer cell genomes." (PMID 34458275, 2021). "In primary breast cancer, the increased ZEB1 suppressed the expression of epithelial marker E-cadherin and induced the EMT process, indicating that the transformed tumor cells with high ZEB1 level lost their epithelial characteristics and developed a mesenchymal/motile phenotype." (PMID 32014049, 2020). "Importantly, we demonstrated concomitantly high expression of Zeb1 and NICD in breast cancer patients with poorly differentiated high-grade tumors, highlighting that dysregulated Notch1-Zeb1 signaling is functionally linked to tumor stem cell traits in breast cancer." (PMID 33046710, 2020). "Notably, breast cancer cells expressing NICD and ALDH1 were predominantly located in the perivascular region close to endothelial cells in PyMT tumors; however, the perivascular colocalization of NICD and ALDH1 was significantly weakened by Zeb1 depletion." (PMID 33046710, 2020). "In nontumor MCF12A mammary epithelial cells and MCF7 breast cancer cells, leptin induces a mesenchymal phenotype, ZEB1 expression, and a “switch” from E-cadherin to N-cadherin, as well as the classic CD24-/CD44+ stem signature, and a larger number of spheres through STAT3." (PMID 33334030, 2020). "Interestingly, ZEB1 binds and represses the GRHL2 promoter in breast cancer." (PMID 32005677, 2020). "Considering the role of ZEB1 in oncogenesis, EMT progression and drug resistance, we hypothesized that the expression of ZEB1 is correlated with a poor response to neoadjuvant chemotherapy and poor prognosis for patients with breast cancer." (PMID 30976202, 2019). "Inhibiting ZEB1-mediated immune suppression, either directly or by inhibiting ZEB1-regulated immune modulators like BMPR2, may be a therapeutic approach to promote antitumor immune activity in breast cancer." (PMID 31780722, 2019). "However, here we find that ZEB1 disruption in MaECs does not affect tumour initiation, growth or metastasis in PyMT-induced breast cancer." (PMID 31324807, 2019). "Since PC4 silencing could increase the migration and invasiveness in breast cancer cell lines, the expression pattern of different MMPs, mesenchymal markers like fibronectin, vimentin and regulators of EMT like, Zeb1 and Zeb2 was investigated upon silencing of PC4 in these cells." (PMID 31839879, 2019). "Thus, we propose that FOXP3 and miR-155 co-operate to down regulate ZEB2, but not ZEB1, in breast cancer cells." (PMID 29963231, 2018). "Triple–negative human breast cancers express high ZEB1 mRNA levels and exhibit features of EMT." (PMID 29744893, 2018).
breast carcinoma (continued). "We conclude that removal of a single EMT‐TF, ZEB1, from an established mesenchymal breast cancer cell, is not sufficient to revert the tumor cells into a more epithelial phenotype, as we also demonstrated for Snail1 and Twist1 in an independent breast cancer model." (PMID 29744893, 2018). "Importantly, the correlation between ZEB1 and ATM, as well as the other seven target genes, were demonstrated by TCGA database analysis, highlighting a predominant role for ZEB1 in inducing ATM expression in breast cancer cells." (PMID 29352223, 2018). "Extensive alternative splicing occurs during EMT, in part mediated by ZEB1, which transcriptionally represses the epithelial splicing regulatory protein genes, favoring expression of spliced isoforms of the FGF receptors that help maintain EMT in breast cancer cells in response to TGFβ." (PMID 29744893, 2018). "The micro‐RNA 200 (miR‐200) gene family is actively repressed by ZEB1 in response to TGFβ signaling; miR‐200 pairs with the ZEB1 and TGFβ2 mRNAs and inhibits their translation, thus forming a double‐negative feedback loop that is critical for breast carcinoma EMT." (PMID 29744893, 2018). "In basal‐type breast cancer cells, high ZEB1 expression was observed even in the absence of TGF‐β." (PMID 28618162, 2017). "Furthermore, clustering 13 breast cancer cell lines with shRNA scores of MZF1, SOX10 and ZEB1, could roughly distinguish TNBC cell lines from nTNBC cell lines." (PMID 28423538, 2017). "Moreover, survival analysis of this breast cancer data set demonstrated that irrespective of the subtype, tumours with high expression of the ‘common ZEB1/YAP target genes' displayed a significant shorter relapse-free and overall survival." (PMID 26876920, 2016). "The EMT transcription factor Zeb1 has bivalent chromatin marks at its gene promoter in non-CSCs of basal breast cancer tissue yet upon appropriate signaling can shift to allow for active transcription of Zeb1, thereby enhancing cell plasticity and activating CSC programs." (PMID 27110512, 2016). "Moreover, immunohistochemical staining of samples from 4 representative subjects confirmed the positive relationship between ZEB1, VEGFA, and CD31 expression, which is consistent with our finding that ZEB1 upregulates VEGFA expression and promotes tumor angiogenesis in breast cancer." (PMID 26882471, 2016). "To this end, we down-regulated the expression of Zeb1, Snail and Slug, chosen due to their prominent involvement in inducing EMT in different cancers and to their roles in generating a TME-Stimulation-induced EMT-like phenotype in Luminal-A breast cancer cells." (PMID 27835603, 2016). "As previously reported, transcription factors ZEB1 and Snail are critical transcriptional regulators of IGF-I/IGF-IR-mediated EMT, and ultimately function as metastasis promoters through the repression of cell adhesion molecule E-cadherin in prostate and breast cancer cells." (PMID 25435948, 2015). "Moreover, in addition to a higher prevalence of LPA1 expression in basal than in non-basal breast cancer cell lines, there was a significant correlation between ZEB1 and LPAR1 in cell line of basal subtypes but not of non-basal subtype." (PMID 26098771, 2015). "In addition, LPA-induced ZEB1 expression in basal breast cancer cells was mediated through a PI3K-dependent but not of a MEK1-dependent signaling pathway." (PMID 26098771, 2015). "The conditioned medium from bone metastatic MDA-BoM-1833, that expressed the highest levels of ZEB1 and of the BMP-inhibitors, led to the strongest osteoclast formation, compared to the parental MDA-MB-231, the lung metastatic MDA-LM2–4175 and the luminal breast cancer cell lines T47D and MCF7." (PMID 25973542, 2015).
breast carcinoma (continued). "In all cases, basal breast cancer cell functions were rescued by co-transfecting the cells with a miR-21 mimic molecule, indicating that LPA-induced basal breast cancer cell migration and invasion was regulated in a miR-21-dependent manner, down-stream of LPA1 and ZEB1 activations." (PMID 26098771, 2015). "The purported tumor suppressive functions of miR-205 in breast cancer is due to direct targeting of several oncogenes such as VEGFA, E2F1, E2F5, PKC epsilon and HER3 reviewed in 16 as well as attenuating epithelial to mesenchymal transition (EMT) by suppressing ZEB1 and ZEB2." (PMID 24098490, 2013). "By ChIP with chromatin from MDA-MB231 breast cancer cells, we could show that endogenous ZEB1 binds to the native promoter region of EPCAM that has five putative binding sites (E-boxes 1–4 and Z-Box-1) for ZEB1." (PMID 23667256, 2013). "No expression for zeb1 was found in breast cancer cells in the epithelial compartment." (PMID 21324165, 2011). "However, the regulatory effect of miR-223 on ZEB1 has not been reported in breast cancer." (PMID 38164285, 2024). "Therefore, we tested the expression of various EMT‐related proteins in breast cancer cells and observed that the levels of several EMT markers, including slug, snail, and vimentin, were increased in CASQ2‐overexpressing cells and the level of ZEB1 was decreased." (PMID 34743414, 2022). "Similarly, SNHG3 expression was dramatically elevated in breast cancer cells and tissues, while overexpression of SNHG3 in MCF-7 band MDA-MB-231 cells induced breast cancer cell proliferation, EMT, migration, and invasion, through regulating miR-186-5p and ZEB1 expression." (PMID 36139687, 2022). "Although our study did not address the causal role of ZEB1/2 in RKIP-mediated regulation of E-cad expression, our results conclusively demonstrated a link between RKIP, Erk, GEF-H1, RhoA, and E-cad expression in triple negative basal epithelial-like breast cancer cell lines." (PMID 34465801, 2021). "For example, in basal like breast cancer cells, Chaffer and colleagues observed that ZEB1 promoter of non-CSCs is maintained in a bivalent configuration and in response to TGFβ, the chromatin switches to an active state leading to the transcription of ZEB1, consequently converting non-CSCs to CSCs." (PMID 32426371, 2020). "Taken together, our results showed that overexpression of ZEB1 could transcriptionally suppress the expression of ERα and miR-190 and led to SOX9 elevation and activation of Wnt/β-catenin signaling, resulting in anti-estrogen resistance therapies in breast cancer." (PMID 30658681, 2019). "Moreover, in the human breast cancer metastasis cohort with lung, liver, and bone metastases, the positive linear correlation between CAM6 and CAM5 mRNA expressions with concomitant E-cad expression was significant, whereas ZEB1 expression correlated negatively with E-cad expression." (PMID 31331982, 2019). "Furthermore, a large set of microRNAs co-regulates expression of both Zeb1 and Zeb2, modulating therefore tumor progression, for example miR-101 in ovarian carcinoma, miR-200 in gastric adenocarcinoma, miR-139 in HCC, miR-205 and miR-448 in breast cancer, and miR-590 in glioblastoma." (PMID 29843425, 2018). "Concomitantly, when the protein levels of EMT transcription factors such as SNAIL, SLUG, ZEB1 and TWIST were investigated, irradiation was found to cause a strong increase of SLUG; however, other EMT transcription factors were not altered by irradiation in MCF7 breast cancer cells." (PMID 27462787, 2016). "In this work, we could further clarify the detailed functions of the ZEB1/miR-200 feedback loop in tumor invasion by identifying MYLK and TKS5 as two novel miR-200 target genes, that are both necessary for invadopodia formation and invasion of breast cancer cells." (PMID 26334100, 2015).